DEPTOR (DEP domain containing MTOR interacting protein)
Diseases named in the same sentence as DEPTOR in open-access papers (continued):
Sharing a sentence is not in itself a finding about the gene and the disease.
pancreatic ductal adenocarcinoma (1 paper, 2014). An infiltrating adenocarcinoma that arises from the epithelial cells of the pancreas. "Here we show that DEPTOR expression is gradually reduced in pancreatic preneoplastic lesions, and completely lost in 99% of pancreatic ductal adenocarcinoma tissues." (PMID 25544749, 2014). "Here we report that while DEPTOR shows a cytoplasmic expression in both normal pancreatic acinar and islet cells in a patchy manner, its expression is reduced in PanIN1 and PanIN2 and completely lost in 100 out of 101 pancreatic ductal adenocarcinoma (PDAC) tissues." (PMID 25544749, 2014).
pituitary adenoma (1 paper, 2021). "For instance, DEPTOR was found to confer the sensitivity of the pituitary adenoma to dopamine agonist and block the proliferation of cells." (PMID 34540820, 2021).
placental insufficiency (1 paper, 2025). Failure of the placenta to deliver an adequate supply of nutrients and oxygen to the fetus. "However, the molecular mechanisms causing increased trophoblast DEPTOR protein expression in placental insufficiency remain to be fully established." (PMID 41203646, 2025).
prostate tumor (1 paper, 2020). "To explore the specific role of DEPTOR in prostate tumorigenesis, we examined potential alterations of DEPTOR expression in prostate tumor tissues compared with adjacent normal tissues." (PMID 31685947, 2020).
tumor (47 papers, 2011 to 2025). "Collectively, our study demonstrated that DEPTOR is a tumor suppressor that inhibits lymphomagenesis upon Pten-loss." (PMID 40169856, 2025). "This causal role of DEPTOR is fully demonstrated by an in vivo rescue experiment, in which suppression of tumor growth by Ube2c KO is fully abrogated by simultaneous Deptor KO." (PMID 36548081, 2023). "In previous work, we have described small inhibitors that bind to the PDZ domain of DEPTOR, prevent DEPTOR/mTOR association in MM cells, induce acute activation of mTOR, and MM tumor cell apoptosis." (PMID 35216969, 2022). "The viability of Deptor−/− mice provided us an opportunity to study the role of DEPTOR in tumorigenesis in combination with inactivation of a tumor suppressor or activation of an oncogene, such as Pten loss or Ras activation." (PMID 31685947, 2020). "In order to determine the molecular mechanisms underlying DEPTOR mediated tumor suppression, AKT/mTOR signaling pathway was tested by western blotting in our established cells lines." (PMID 26893358, 2016). "In tumor development and progression, DEPTOR activity is associated with cell growth, apoptosis, autophagy, and the epithelial-mesenchymal transition." (PMID 27144580, 2016). "In cell culture settings, DEPTOR mainly acts as a tumor suppressor, since its loss activates mTORC1 and mTORC2 to promote growth and survival of cancer cells." (PMID 27955654, 2016). "In cell culture settings, DEPTOR mainly acts as a tumor suppressor, since DEPTOR loss activates mTORC1 and mTORC2 and promotes growth and survival of multiple cancer cell lines." (PMID 25544749, 2014). "From an initial set of 76 patients diagnosed with PTC, we utilized qRT-PCR to assess the expression levels of four characteristic genes associated with OSPTCC subtypes (APOE, APOC1, DEPTOR, and SQSTM1) in patient tumor samples." (PMID 40650680, 2025). "Overall, we elucidated a novel mechanism through which DEPTOR feedback activates the PI3K–Akt signal to change the metabolism of tumor cells." (PMID 37469018, 2023). "In in vitro cell culture studies, DEPTOR was initially characterized as a tumor suppressor, since its expression was downregulated in multiple tumors, and its depletion enhanced cell growth and survival by activating mTORC1 and mTORC2 signaling." (PMID 36548081, 2023). "Together, these data provided support for the model suggesting that PUM1 positively regulates DEPTOR in a clinical context as a tumor promoter." (PMID 37469018, 2023). "In patient group 2, the gene DEPTOR, which is known to inhibit lung tumorigenesis, is negatively correlated with tumor variance (red samples), suggesting its potential role as a diagnostic biomarker for differentiating patients at high risk of progression." (PMID 36902378, 2023). "Collectively, these results demonstrated that the tumor-suppression phenotype resulting from Ube2c deletion was mainly mediated via DEPTOR accumulation and subsequent inactivation of mTORC1/2 signaling in the KrasG12D lung tumorigenesis model." (PMID 36548081, 2023). "The downregulated genes (DEPTOR, DPEP1, NAT8, and SUSD2) in the tumor and thrombus were associated with a worse survival rate when the gene was less expressed in the tumor, and the same correlation was observed for the upregulated genes (PLOD2 and SLC7A5)." (PMID 37328520, 2023). "Collectively, these data show that KDM6A expression correlates with DEPTOR expression in human tumours and is accompanied with activation of mTORC1." (PMID 34509979, 2022). "The expression levels of ZBTB32 and DEPTOR were higher in normal tissues than in tumor tissues (P <0.001), while the opposite was true for SPAG4 expression (P <0.001)." (PMID 35095893, 2021). "According to the data in The Cancer Genome Atlas (TCGA)-Genotype-Tissue Expression (GTEx) Database, DEPTOR was predicted to be highly expressed in tumor samples." (PMID 34540820, 2021).
tumor (continued). "Given that DEPTOR can act as either a tumor suppressor or an oncoprotein in cell culture settings, it is necessary to examine the role of DEPTOR in breast tumorigenesis in vivo, particularly in Deptor-knockout (KO) mouse models." (PMID 33995662, 2021). "The vertebrate-specific DEP domain-containing mTOR interacting protein (DEPTOR), an oncoprotein or tumor suppressor, has important roles in metabolism, immunity, and cancer." (PMID 34519268, 2021). "Surprisingly, we found that in 43 out of the 67 paired cases (64%), DEPTOR expression was higher in tumor tissues than in their corresponding tumor-adjacent normal tissues, in contrast to the alterations in DEPTOR mRNA levels." (PMID 33995662, 2021). "Expression of DEPTOR, a negative regulator of mTORC1/2, is known to be low in many cancer cells, however, DEPTOR acts as a tumor suppressor or oncogene, depending on the cellular context of cancers." (PMID 32495998, 2020). "As a natural inhibitor of mTORC1 and mTORC2, DEPTOR is generally considered as a tumor suppressor, which promotes protein synthesis, cell growth and survival." (PMID 31685947, 2020). "Collectively, our study demonstrates that DEPTOR is a tumor suppressor in the prostate, and its depletion promotes tumorigenesis via the activation of mTORC1 and mTORC2 signals." (PMID 31685947, 2020). "In cell culture settings, opposite roles of DEPTOR have been reported, either acting as a tumor suppressor by inactivating mTORC1/2 or acting as an oncogene by relieving the feedback inhibition from S6K1 to PI3K, leading to AKT activation." (PMID 31685947, 2020). "Given that mTOR signaling is frequently activated in many human cancers, DEPTOR usually acts as a tumor suppressor, by inhibiting mTOR, to suppress cell growth, and survival via inactivation of AKT5,6." (PMID 33184290, 2020). "As a naturally occurring inhibitor of both complexes, DEPTOR functions as a putative tumor suppressor by suppressing protein synthesis, cell growth, proliferation, and survival." (PMID 31685947, 2020). "We found that DEPTOR was frequently overexpressed in HCC tissues, and its high expression was associated with high serum AFP levels, increased tumor size, vascular invasion and more advanced TMN and BCLC stage, as well as an overall poor prognosis." (PMID 31228948, 2019). "We then performed animal experiments to determine the effect of DEPTOR downregulation on tumor growth in vivo." (PMID 31228948, 2019). "We further examined the role of DEPTOR in HCC metastasis by establishing an ectopic tumor metastasis model in nude mice." (PMID 31228948, 2019). "DEPTOR significantly promotes the growth of tumor cells in vivo and in vitro by inhibiting mTOR, which releases the negative feedback on the insulin PI3K/AKT pathway and therefore promotes cell survival and prevents apoptosis." (PMID 31228948, 2019). "DEPTOR is an mTOR-binding protein that inhibits mTORC2 signalling, so it is not surprising to find that DEPTOR expression is dramatically reduced in many tumour tissues, including oesophageal squamous cell cancer." (PMID 29301334, 2018). "Recent studies of DEPTOR have focused on its roles in tumor development and progression, whereby it affects cell growth, apoptosis, autophagy, and the endoplasmic reticulum stress response." (PMID 29670094, 2018). "A potential role of DEPTOR as a tumor suppressor or as an oncogene, depending on cell context, has also been described." (PMID 28420429, 2017). "For example, DEPTOR acts as a tumor suppressor by blocking mTORC1 activity to inhibit protein synthesis and cell proliferation." (PMID 28349073, 2017). "In in vitro studies, ectopic expression of DEPTOR in KYSE-150 ESCC cells that has a relative lower level of DEPTOR significantly suppressed cellular proliferation, migration and invasion, as well as inhibited the in vivo tumor growth in a nude mice model." (PMID 26893358, 2016).
tumor (continued). "Meanwhile, the tumor suppressive role of DEPTOR was also confirmed in another cell line KYSE-510 by knockout DEPTOR expression with CRISPER/Cas9 system, as KYSE-510 cells express a higher level of DEPTOR." (PMID 26893358, 2016). "In this study, we firstly reported that DEPTOR expression is significantly decreased in tumor tissues of ESCC patients, and predicts a poor five-year survival rate." (PMID 26893358, 2016). "Here we show that DEPTOR expression is significantly reduced in tumor tissues, and predicts a poor survival of ESCC patients." (PMID 26893358, 2016). "In order to study a potential role of DEPTOR in regulation of tumor progression, several ESCC cell lines, KYSE-150, KYSE-510 and KYSE-190, and normal esophageal squamous epithelial cell HET-1A were used." (PMID 26893358, 2016). "The results showed that overexpression of DEPTOR significantly suppressed growth of xenografts in nude mice from 15 days after inoculation as well as the tumor weights for about 55.2% at the end of study (p = 0.0103)." (PMID 26893358, 2016). "The result showed that mRNA expression of DEPTOR was significantly reduced in tumor tissues as compared to that in paired adjacent normal tissues in ESCC patients (p < 0.0001)." (PMID 26893358, 2016). "DEPDC6 (DEP domain-containing mTOR-interacting protein or DEPTOR) is a negative regulator of mTOR signaling and is therefore expected to be a tumor suppressor." (PMID 23213280, 2012). "Furthermore, DEPTOR expression differs among tissues, and some studies have demonstrated that DEPTOR expression is significantly dependent on the tumor type." (PMID 41249115, 2025). "Furthermore, the tumor-suppression effect of Ube2c KO is achieved largely by accumulated DEPTOR as a substrate of UBE2C." (PMID 36548081, 2023). "As a natural mTORC1/2 inhibitor, DEPTOR is generally considered a tumor suppressor in most cases." (PMID 36548081, 2023). "Thus, our study clearly demonstrated that the UBE2C/DEPTOR axis is an oncogene-tumor suppressor cascade that regulates lung tumorigenesis triggered by KrasG12D." (PMID 36548081, 2023). "The subcutaneous tumor transplantation experiment and abdominal metastasis experiment in mice further confirmed that overexpression of DEPTOR after silencing PUM1 could restore the proliferation and metastasis of cells in vivo." (PMID 37469018, 2023). "However, the role of AR mediated gene repression in PCa progression and treatment is complex as the AR has been shown to also directly repress tumor suppressor genes such as DEPTOR, E-cadherin, c-Met, and GPER1." (PMID 35018219, 2022). "The role of DEPTOR in inhibiting tumor progression may be attributed to its ability to repress cell migration, which is necessary in metastasis and cancer progression." (PMID 35078427, 2022). "mTOR has critical roles in tumor progression, and mTOR complex 1 (mTORC1), is composed of mTOR bind to Raptor, GβL, and DEPTOR and could be inhibited by FDA approved drug Rapamycin." (PMID 35690832, 2022). "Studies that have investigated the role of DEPTOR in cancer indicate that DEPTOR levels are generally low across several tumor types, and that rescue of DEPTOR is an effective anti-cancer therapy, warranting further study of this novel protein in mTOR-dependent processes." (PMID 36388131, 2022). "In addition, we analyzed RNA-seq expression of ErbB2 and DEPTOR in ErbB2-positive BRCA tumor tissues from TCGA." (PMID 33854045, 2021). "Interestingly, DEPTOR can act either as a tumor suppressor or oncogene in a context-dependent manner 1, 6, 7; however, the molecular mechanisms remain elusive." (PMID 33995662, 2021). "DEPTOR acts as a tumour suppressor by blocking mTORC1 and mTORC2, inhibiting cell proliferation." (PMID 32372061, 2020). "Moreover, high expression of DEPTOR was associated with high serum AFP levels, increased tumor size, vascular invasion and more advanced TMN and BCLC stage." (PMID 31228948, 2019).
tumor (continued). "To date, only few studies focused on the role of DEPTOR in tumor metastasis." (PMID 31228948, 2019). "Since vascular invasion frequently indicates the ability of tumor metastasis, the results suggest that DEPTOR may be involved in HCC metastasis." (PMID 31228948, 2019). "In addition, DEPTOR expression levels were lower at the tumor invasive front than in the tumor center, which was similar to the expression pattern of ASS1." (PMID 28358054, 2017). "By blocking mTOR activity, DEPTOR in general should act as a tumor suppressor." (PMID 26992219, 2016). "In addition, in vivo assays further revealed that tumor growth was significantly inhibited in xenografts with ectopic DEPTOR expression as compared to untreated KYSE150 cells, and was markedly enhanced in DEPTOR knockout KYSE-510 cells." (PMID 26893358, 2016). "This suggests that activation of mTORC1 occurs downstream of the PI3K–PDK1–AKT cascade in tumours harbouring IDH1 mutations, supporting the notion that 2HG-mediated inhibition of KDM4A affects the stability of DEPTOR leading to mTOR activation independently of the PI3K/AKT/TSC1-2 pathway." (PMID 27624942, 2016). "Similarly, in KYSE-510 cells, ablation of DEPTOR significantly promoted tumor growth in nude mice as compared with normal KYSE-510 cells." (PMID 26893358, 2016). "Thus, accumulation of PHLPP1 or DEPTOR upon SAG knockdown plays at least in part a causal role in suppression of tumor cell growth and reverse of tumor cell phenotypes." (PMID 27955654, 2016). "P21 upregulation also occurs during tumor regression in vivo when DEPTOR is silenced." (PMID 25568666, 2014). "Interestingly, DEPTOR could act either as a tumor suppressor or as an oncogene in a manner dependent of cellular context or tissue environment." (PMID 40169856, 2025). "However, we found a significant accumulation of DEPTOR, a tumor suppressor and a naturally occurring inhibitor of mTORC1/2, implying that the DEPTOR/mTORC pathway could be involved in the growth-suppressing effect of UBE2C knockdown." (PMID 36548081, 2023). "Therefore, the overexpressed DEPTOR may inhibit the mTOR signaling pathway and thus exerted a tumor suppressor effect." (PMID 35507914, 2022). "Importantly, the interaction of DEPTOR with ErbB2 enhances the functions of ErbB2 in cell proliferation and survival, which implies that DEPTOR might promote ErbB2-mediated breast tumorigenesis and have oncogenic characteristics." (PMID 33995662, 2021). "Thus, using Deptor-KO mouse models are the only way to clearly demonstrate the in vivo physiological role of DEPTOR in tumorigenesis and whether it is functioning as a tumor suppressor or an oncoprotein." (PMID 31685947, 2020). "Thus, we demontrated that DEPTOR negatively regulated the activation of AKT/mTOR pathway which may be responsible for its tumor suppressive function." (PMID 26893358, 2016). "Therefore, the potential role of DEPTOR as an oncogene or a tumor suppressor may be cell context or tissue specific." (PMID 26893358, 2016). "Among these six hub genes, DEPTOR, DPEP1, NAT8, and SUSD2 were expressed at their highest levels in normal tissues, whereas PLOD2 and SLC7A5 were expressed at their highest levels in tumor thrombi." (PMID 37328520, 2023). "It was found that RNF7 act an imperative role in tumor proliferation and radiation-resistance through inactivating NF-κB and mTOR pathway or assembling tumor suppressive proteins, including NF1, DEPTOR, procaspase-3, p21, p27, NOXA, and BIM." (PMID 36644576, 2023). "To determine whether ErbB2 degradation triggered by DEPTOR knockdown plays a causal role in the inhibition of cell proliferation and survival, we ectopically expressed ErbB2-YVMA, a constitutively active ErbB2 A775-G776insYVMA mutant from human tumor patients 23, in DEPTOR-depleted cells." (PMID 33995662, 2021).